TLR9 (toll like receptor 9)
Diseases named in the same sentence as TLR9 in open-access papers (continued):
Sharing a sentence is not in itself a finding about the gene and the disease.
tumor (continued). "Furthermore, TLR9 agonists can exert antitumor effects by suppressing angiogenesis, blocking tumor growth through cell cycle arrest, or inducing autophagy." (PMID 36611945, 2022). "Additionally, in EAC tumors, expression of Toll-like receptor-9 (TLR-9) is correlated with high pathological tumor stage, distant organ metastases, high tumor grade, and decreased 10-year survival rates." (PMID 35511379, 2022). "Similarly, administration of CpG oligo dinucleotides (ODN), a TLR9 agonist, primes tumor-draining lymph node DCs that produce IFN-α/β resulting in T cell activation." (PMID 36230990, 2022). "However, it is intriguing to note that intracellular expression of c-MYC, a recognised proto-oncogene located downstream of TLR7 and TLR9, can modify tumour cell sensitivity to Irofulven." (PMID 35801728, 2022). "Finally, taking for granted the prognostic significance of tumor mutational status, KRAS and BRAF mutations were correlated with TLR9—T1237C, TLR9—T1486C polymorphisms, and TLR9—T1486C, respectively." (PMID 36139567, 2022). "In preclinical models, blocking the IL-8-CXCR2 axis or TLR9 activation delayed tumor progression." (PMID 36059520, 2022). "Chemical coupling of a polyspecific integrin-binding peptide (PIP) with the TLR9 agonist CpG to form PIP-CpG was found to induce tumor regression and enhance therapeutic efficacy with systemic delivery of PIP-CpG compared to non-targeted CpG in invasive mouse models of breast and pancreatic cancer." (PMID 36365103, 2022). "For patients with allogeneic transplants, intratumoral anti-PD-1 treatment combined with TLR9 agonist can ensure a strong anti-tumor immune response while avoiding severe transplant rejection caused by systemic immunotherapy, reflecting the unique effectiveness and safety of intratumoral injection." (PMID 36713427, 2022). "However, study has also shown that uptake of tumor-released cell-free mtDNA by TLR9 can evoke anti-tumor immune activity in dendritic cells (DCs) and tumor-specific CTLs." (PMID 39871923, 2022). "Indeed, it is well known that TLR9 expression is enhanced in OSCC compared to normal tissue and it has significantly been associated with tumor size, clinical stage and proliferative status." (PMID 35990685, 2022). "TLR7 and TLR9 of pDCs were activated to produce IFN-α for tumor-killing." (PMID 36618371, 2022). "We showed here that ligation of some TLRs, and especially of TLR9, may prevent the development of subsequently inoculated tumor cells in normal immunocompetent animals." (PMID 36714124, 2022). "Additionally, numerous studies have indicated that, in addition to its antitumor biological activity, TLR9 can enhance tumour cells' sensitivity to chemotherapy by increasing chemotherapy-induced apoptosis and decreasing tumour cell proliferation." (PMID 35801728, 2022). "Finally, high-dose radiation in combination with a TLR9 agonist in pre-clinical tumor models enhanced anti-tumor immune responses via increasing activated CD4+ and CD8+ T cells within the tumor microenvironment." (PMID 35055015, 2022). "CpG ODN quickly activates T and B lymphocytes, promote the production of Th1-type pro-inflammatory cytokines, and directly acts on DCs through the TLR9 signaling pathway to induce the maturation/activation of DCs, which has a broad application prospect in anti-tumor therapy." (PMID 35251013, 2022). "TLR9 was barely detectable in PRMs at baseline and at week 3 after tumor inoculation, suggesting that TLR9 in other peritoneal cell types might regulate the retention of PRMs." (PMID 36278484, 2022). "Indeed, 88% of the patients that drank more than 60g alcohol/day and were cataloged as heavy alcohol consumers exhibit tumor samples that showed an enhanced expression of TLR9." (PMID 35990685, 2022). "Likewise, Toll-like receptor 9 (TLR-9) describes a proper alternative target to obtain a meaningful immune activation into the tumor site." (PMID 35785199, 2022).
tumor (continued). "TLR9 showed low correlation with both immune and stromal scores, which may be due to the low expression of TLR9 in all the tumor samples." (PMID 35937402, 2022). "Analysis of TLR9 level and grading, as well as TN stage, revealed that TLR9 level was higher in poorly differentiated tumors (G3), in extensive tumor dimensions (T3–T4) and in lesions with lymph nodes involvement (N3–N4) but these differences were not statistically significant." (PMID 34439137, 2021). "Moreover, siRNA of TLR9 EVs inhibited invasive behaviors, including extension of protrusions and collagen degradation, evoked by tumor cell EVs in glutamine-starved recipient cells." (PMID 34623384, 2021). "Deletion of the Tlr9 or Ifnar1 gene rendered the vaccine ineffective in blocking tumor formation." (PMID 34194942, 2021). "TLR5, TLR7 and TLR9 are the best examples of TLRs that could reinforce the anti‐tumour activity of DCs." (PMID 33336901, 2021). "Moreover, the relationship between TLR9 levels and TN classification and histological differentiation of the tumor (G) was analyzed as well as the correlation between serum level of TLR9 and examined cytokines." (PMID 34439137, 2021). "TLR9 level was measured in homogenate of tumor tissue and in serum." (PMID 34439137, 2021). "One possibility may be through the use of increased DNA sensing by TLR9 on CD8+ T cells in mice treated with DNAse I. It has been demonstrated that the TLR9 agonist effectively increases tumor infiltration by CD8+T cells." (PMID 34771497, 2021). "Similar phenomena were reported for other immunotherapy strategies; for example, CpGs which act as TLR-9 agonists, show increased potency when delivered by a nanoparticle, and this has been attributed to prolonged tumor residence and altered intratumoral distribution." (PMID 34575893, 2021). "CpG-ODN is intrinsically vulnerable to nuclease and thus soluble TLR9 agonists delivered in situ may be rapidly degraded and diffuse out of the tumor." (PMID 35008305, 2021). "TLR4−/−, TLR7−/− and TLR9−/− untreated tumors presented significantly small volume compared to WT untreated tumors indicating that these TLRs could be involved in normal tumor development." (PMID 34341449, 2021). "It has been demonstrated that agents that can induce the differentiation of MDSCs include vitamin A and D, all-trans retinoic acid (ATRA), IL-12, the activation of TLR9, taxanes, beta-glucan particles, the inhibition of tumor-derived exosomes, and very small size proteoliposomes." (PMID 34248142, 2021). "Intratumoral SD-101, a synthetic CpG oligonucleotide that stimulates Toll-like receptor 9 (TLR9) and is directly injected into the tumor site, has been shown to increase effectiveness of immune activation at the tumor site when used in combination with PD-1 inhibitors." (PMID 33613847, 2021). "Importantly, TLR-9 agonists efficiently mediate inflammatory processes that lead to the enhancement in the uptake and killing of tumor cells." (PMID 34202080, 2021). "Furthermore, strong cytoplasmic TLR9 immunoreactivity correlated with high pathological tumor stage, positive lymph nodes, distant organ metastases, high tumor grade, tumor unresectability, and decreased 10-year survival rates." (PMID 34439930, 2021). "The finding suggested that treatments of MGN1703 or other TLR9 agonists may favor the tumor environment with a lower CD86+ B cell population, especially regulatory B cells." (PMID 35056969, 2021). "TLR9 agonist CpG has been reported to enhance infiltration of CD8+ T cells in the tumor." (PMID 34771674, 2021). "Furthermore, TLR9 agonists have been shown to have therapeutic value, mainly through stimulating an anti-tumor response." (PMID 32961746, 2020). "We further investigated the in vivo anti-tumor efficacy of OCT4-3 + TLR9." (PMID 32296581, 2020). "DAMPs may also activate TLR9 on human breast, prostate and lung cancer cells to trigger tumor invasion and metastasis." (PMID 32817793, 2020).
tumor (continued). "Notably, significant tumor inhibition was achieved in OCT4-3 + TLR9-treated BABL/c mice, prophylactically." (PMID 32296581, 2020). "Similarly, melanoma-specific peptide vaccines with TLR9 agonists also demonstrated tumor antigen-specific T-cell activation and improved antitumor response in mouse models." (PMID 33008010, 2020). "By using the human pDC cell line GEN2.2, it has been demonstrated that TLR7 and TLR9 stimulation can induce a TRAIL-mediated cytotoxic activity in pDCs that could participate to the tumor cell clearance." (PMID 32054102, 2020). "Finally, CpG oligodeoxynucleotides are agonists of TLR9 and are being tested in several tumor types and in some clinical trials." (PMID 32984007, 2020). "In this report, we demonstrated that the DOTAP liposome could carry TLR2-fused antigens and TLR9 agonists to enhance DCs activation and reduce Tregs in the tumor microenvironment." (PMID 32231003, 2020). "Thus, cancer therapy using a combination of TLR9 activation and immune checkpoint blockade can result in more robust and more specific tumor killing." (PMID 32547560, 2020). "Therefore, TLR2 and TLR9 signaling can synergistically induce robust CTLs and modify the tumor microenvironment toward regression." (PMID 32231003, 2020). "For example, triggering TLR responses (such as by administering a TLR9 agonist) in tumor cells can lead to the induction of tumor cells death 14, which, under certain conditions, is associated with antitumor immunity induction by mechanisms involving immunogenic or immunostimulatory cell death." (PMID 32483468, 2020). "Notably, immunohistochemical staining of CD3+ cells in tumor tissues revealed a substantial number of CD3+ T cells in the tumor sections of OCT4-3 + TLR9-treated mice, suggesting that T cells were likely effector cells mediating tumor regression." (PMID 32296581, 2020). "Alternatively, well-known agents targeting IFNG, IL2, or TLR9 might be considered as adjuncts in tumor types already demonstrating the T cell-inflamed phenotype." (PMID 33106165, 2020). "Importantly, the results showed that cytotoxic T lymphocyte activity and the inhibition of tumor growth were enhanced in mice immunized with OCT4-3 combined with TLR9." (PMID 32296581, 2020). "Moreover, DCs purified from tumor draining lymph nodes of wildtype mice were able to stimulate E7-specific CTLs 10 times more efficiently than DCs from TLR9−/− mice." (PMID 31619293, 2019). "Similarly, tumor-associated pDCs showed decreased IFNα secretion upon TLR7 and TLR9 stimulation in breast and ovarian cancers." (PMID 30987228, 2019). "The mtDNA was shown to activate TLR9 signaling during hypoxia to induce tumor growth." (PMID 31205871, 2019). "It has been already demonstrated that the CpG-enriched OAd could stimulate the TLR9 response and that the anti-tumor immune response was related to the NK recruitment and activity." (PMID 31291991, 2019). "TLR9 mRNA expression was significantly reduced in NPC patients with advanced state of the disease (patients with larger tumor size (T4)) (p = 0.013) and advanced clinical stage (SIII-SIV) (p = 0.0374) compared to patients with early state of the disease (T1, T2) (SI-SII), respectively." (PMID 31886298, 2019). "One strategy to turn an immunologically cold tumor hot is to promote activation of antigen presenting cells (APC) by targeting the endosomal TLRs TLR3, TLR7, TLR8, TLR9, or by targeting the ER-associated signalling molecule stimulator of interferon genes (STING)." (PMID 31511088, 2019). "In this setting, the TLR9 agonist converts the injected tumor into an in situ vaccine and the checkpoint provides the conditioning of uninjected tumor sites and protection from attenuation necessary for the mobilized T cells to mediate effective abscopal responses." (PMID 31771649, 2019).
tumor (continued). "Mechanistically, improved CD8 to Treg ratios in the uninjected tumor appeared critical for conditioning an environment in which T cell mobilized from the TLR9-treated lesion could flourish." (PMID 31771649, 2019). "Since TLR9 is known to broadly activate both the innate and adaptive immunity, TLR9-triggered immune activation can re-activate immune surveillance to effectively recognize tumor-specific antigens on cancer cells of tumor patients." (PMID 30621769, 2019). "Agonistic anti-CD40 mAb (which activates effector macrophages) and CpG-oligodeoxynucleotides (a toll-like receptor 9 agonist that acts as a danger signal) induce tumor destruction via innate effector cells, leading to increased presentation of tumor antigens and an adaptive T cell response." (PMID 31810498, 2019). "TLR9 is a cell-surface transmembrane receptor that is upregulated under conditions of cellular or environmental stress and is known to be expressed on myeloid-derived cells in the tumor microenvironment." (PMID 31671769, 2019). "The TLR9 activation that resulted from the presence of CpG inside the virus allowed the activation of NK cells and cytokine production that were responsible of the tumor regression in nude mice." (PMID 31291991, 2019). "Indeed, it has been shown that stimulation of TLR9 activates human plasmacytoid dendritic cells and B cells, inducing a potent innate immune response, in preclinical tumor models as well as in patients." (PMID 31086100, 2019). "Finally, another way to enhance the ICI responses is to combine them with intratumoral immunotherapy (e.g., with a TLR9 agonist, PAMPs or Ox40 Ab,) or to use oncolytic viruses to increase tumor neo-antigens." (PMID 31336685, 2019). "Both CTLA-4 and PD-1 blockade could potentiate in situ vaccination through intra-tumoral TLR9 activation with systemic administration, while local administration only effected sub-therapeutic improvements to the uninjected tumor." (PMID 31771649, 2019). "We explored whether agonists of TLR9 could augment innate immunity to promote tumor regression alone or in combination with T cell checkpoint blockade." (PMID 31771649, 2019). "All these results show that CpG ODN TLR9 stimulation is the potent enhancer of tumor response and as such has a potential to improve clinical radiotherapy bearing in mind that standard CpG oligonucleotides have been shown to be highly active in murine models while showing limited activity in humans." (PMID 31886298, 2019). "Furthermore, the synergy in the anti-CD40, CpG, and monophosphoryl lipid A (MPL) treatment was observed to activate TAMs via CD40/TLR9 ligation to kill tumor cells in vitro and inhibit tumor growth in vivo." (PMID 28660349, 2018). "Similarly, targeting TLR9 with CpG oligodeoxynucleotide improved tumor response to radiation in preclinical models." (PMID 30558196, 2018). "STAT3 inhibition and TLR9 immunostimulation disrupt the tolerogenic effects of the tumor microenvironment and thereby lead to potent antitumor immune responses in a variety of preclinical tumor models in mice." (PMID 29921770, 2018). "This suggests that high tumor TLR9 expression protects from relapses in these malignancies." (PMID 28886076, 2017). "Members of the TLR family, including TLR9, are often ectopically expressed in tumors, can induce tumor invasion in vitro, and may be an indicator of poor prognosis in vivo." (PMID 28744288, 2017). "Finally, there is also a possible link between the post-menopausal status, tumor TLR9 expression and adjuvant zoledronate anti-tumor efficacy." (PMID 27888633, 2016). "An increase in BMD was also detected in the zoledronate-treated, TLR9 shRNA tumor-bearing mice." (PMID 27888633, 2016). "Interestingly, the study of the effects of mycobacteria in murine tumor models led to the identification of Toll-like receptor 9 (TLR-9) agonists (CpG-rich DNA motifs)." (PMID 27141395, 2016).
tumor (continued). "In addition, TLR5, TLR7, and TLR9 activation promoted tumor growth in different animal models of cancer." (PMID 28116318, 2016). "Taken together, our new results suggest that tumor TLR9 expression could mediate these tumor-promoting effects in both ER-positive and ER-negative breast cancer cells." (PMID 27888633, 2016). "These patients have triple-negative disease (TNBC) with low tumor TLR9 expression upon diagnosis." (PMID 27888633, 2016). "Indeed, the FDA recently approved the TLR2/TLR4 agonist Bacillus Calmette-Guérin (BCG), the TLR2/TLR4 agonist monophosphoryl lipid A (MPL) and the TLR9 agonist imiquimod as anti-tumor agents." (PMID 25871398, 2015). "TLR9 expression was also reported to be significantly elevated in the tissues of oral squamous cell carcinoma as well as periodontitis, and increased receptor expression was correlated with increased tumor size and clinical stage." (PMID 25999952, 2015). "Taken together, our results indicate that simultaneous activation of TLR9 and attenuation of A20 expression in DCs using in vivo deliverable CpG-siRNA conjugate is capable of inducing a strong and specific immune response against an established tumor." (PMID 26327508, 2015). "What then accounts for their synergistic anti-tumor activity (particularly since TLR7 triggering may inhibit cytokine secretion induced by TLR9 agonists) ?" (PMID 26343193, 2015). "Such tumor TLR9-mediated inflammation might then amplify the anti-tumor immune response, eradicate microscopic disease and through this mechanism, translate into cure." (PMID 25101078, 2014). "Understanding why TLR9 expression levels remain low in some TNBC tumors in the hypoxic tumor microenvironment might reveal novel therapeutic opportunities." (PMID 25101078, 2014). "The anti-tumor effects of rlipo-E7m/CpG were lost in the TLR9-knockout mice." (PMID 24642245, 2014). "Studies from pre-clinical TNBC models suggest that tumor TLR9 expression might affect tumor immunophenotype or be required for chemotherapy-induced anti-tumor immune response." (PMID 25101078, 2014). "Specifically, high tumor TLR9 expression predicts good prognosis among TNBC patients." (PMID 25101078, 2014). "The activation of TLR9 on cancer cells could prevent apoptosis in cancer cells and stimulate proliferation of tumor cells." (PMID 24932259, 2014). "The release of demethylated DNA from lysed tumor cells will activate the innate immune response via the TLR9 pathway, which leads to the release of cytokines and the recruitment of immune effector cells that will augment the adaptive immune response against CT antigens." (PMID 25960928, 2014). "Pre-clinical studies suggest that TLR9 expression may affect tumor immunophenotype and contribute to the immunogenic benefit of chemotherapy." (PMID 25101078, 2014). "How TLRs might be controlled by other events occurring during tumor development is illustrated by the regulation of TLR9 by insulin growth factor 1 (IGF1)." (PMID 25411122, 2014). "Finally, aiming to increase tumor TLR9 expression prior to chemotherapy should be considered a therapeutic opportunity in the TNBC patients that have low tumor TLR9." (PMID 25101078, 2014). "TLR-9 engagement has been shown to exert both antitumor and tumor promoting effects." (PMID 28548068, 2014). "This hypothesis requires a detailed analysis of tumor TLR9-dependent immune response to chemotherapy in immune-competent pre-clinical cancer models." (PMID 25101078, 2014). "A better understanding of the complex interaction of TLR-9 agonists with the tumor and its microenvironment may have a major value for the clinical development of TLR-9 agonists." (PMID 28548068, 2014). "Similar weights of the vehicle-treated mice suggested to us that TLR9 expression in the tumors may be an important determinant of chemotherapy-induced inflammation and activation of anti-tumor immunity." (PMID 25101078, 2014).